CD44 (CD44 molecule (IN blood group))
Diseases named in the same sentence as CD44 in open-access papers (continued):
Sharing a sentence is not in itself a finding about the gene and the disease.
ovarian carcinoma (continued). "Thought-provokingly, the most markedly upregulated gene in APG-2449 responders was CD44, which is a marker for CSCs in ovarian cancer." (PMID 35820889, 2022). "In our research, we showed that exosomes derived from ovarian cancer cells lead to an increase in the expression of the CD44 gene in stimulated fibroblasts." (PMID 36012171, 2022). "For instance, the migration and invasion of low-metastatic ovarian cancer cells were enhanced due to exosome-involved transfer of CD44 from high-metastatic ovarian cancer cells." (PMID 35024437, 2022). "A significantly lower increase in CD44 expression was observed in the treatment of fibroblasts with exosomes derived from ovarian cancer cells treated with α-mangostin and/or cisplatin." (PMID 36012171, 2022). "Even though behaving as a CD44 agonist, A6 treatment reduced the migration of cancer cells in vitro and demonstrated increased progression-free survival in patients with ovarian cancer with a positive safety profile." (PMID 35767191, 2022). "The CD44+/CD117+ cells have the potential to be transformed into epithelial ovarian cancer (EOC) cell types." (PMID 36046821, 2022). "As for paclitaxel resistance, ovarian cancer has been reported to exhibit higher levels of CD44 expression than paclitaxel-sensitive cancer cells." (PMID 35595817, 2022). "Triple-positive (CD24+/CD44+/EpCAM+) cells isolated from ovarian cancer patients exhibit clonogenic potential and chemoresistance to cisplatin and doxorubicin." (PMID 34064635, 2021). "For instance, miR-34a repressed CD44 expression in prostate CD44+ CSCs, resulting in metastasis and regeneration inhibition, and miR-199a-mediated targeting of CD44 in ovarian cancer-initiating cells suppressed tumourigenesis and multidrug resistance." (PMID 34944493, 2021). "Contrary to other CSC markers, i.e., CD133, CD44 is widely expressed in ovarian cancer cells and was highly expressed in the samples analyzed in this study." (PMID 34680456, 2021). "The high expression of CD44 in tumor cells enables it as a well-characterized targeted receptor for breast and ovarian cancer stem cells, and CD44 can form complexes with hyaluronan (HA) which can trigger the endocytosis by tumor cells." (PMID 33787431, 2021). "Surface CD44 expression levels of these human ovarian cancer cell lines were evaluated by flow cytometry." (PMID 34680456, 2021). "DLX4 also induced the expression of CD44 in ovarian cancer cells, and inhibition of CD44 abolished DLX4′s ability of DLX4 to promote tumor-mesothelial cell interactions in these cells." (PMID 34203994, 2021). "In human ovarian cancer cell lines overexpressing CD44, the encapsulated glycosylated paclitaxel liposomes (gPTX-L) conjugated with anti-CD44 antibody efficiently enhanced cytotoxicity in vitro and in vivo, suppressing tumour growth in vivo." (PMID 34944493, 2021). "Many studies have also been conducted to investigate the relationship between CD44 expression and ovarian cancer progression and prognosis with contradictory results." (PMID 34944493, 2021). "A previous study indicated that carboplatin induced CD44 expressing ovarian cancer cells to produce HA, which can contribute to chemoresistance by regulating ATP binding cassette transporter expression." (PMID 34680456, 2021). "A recent meta-analysis also revealed that CD44 expression was significantly associated with a high TNM stage and poor OS in ovarian cancer patients." (PMID 34944493, 2021). "For example, molecules such as CD44 and miR‐99a‐5p in exosomes derived from ovarian cancer cells can promote the MMT of HMrSV5 cells, leading to adhesion and metastasis of ovarian cancer cells." (PMID 34725902, 2021). "CD44 was shown to mediate ovarian cancer cell adhesion to peritoneal mesothelial cells by binding cell surface HA, and thus promotes intraperitoneal ovarian cancer spread." (PMID 34680456, 2021).
ovarian carcinoma (continued). "For instance, the CD44+/CD24- ovarian cancer cells have CSC-like properties such as tumor-initiating ability and invasion." (PMID 34064635, 2021). "CD44+ cells have been identified in primary tissues, metastatic tissues, and malignant ascites of ovarian cancer; one hundred CD44+/CD117+ cells are sufficient to propagate the original tumor, but CD44-/CD117- cells are not." (PMID 34064635, 2021). "CD44 expression has been shown to be associated with CSC-like properties in a variety of tumors, including ovarian cancer." (PMID 34680456, 2021). "In line with this, ovarian cancer patients who co-expressed both CD44 and MMP-14 had a poorer prognosis." (PMID 34944493, 2021). "CD44 targeted therapy was shown to effectively inhibit ovarian cancer dissemination, abrogate ascites, and prolong survival time." (PMID 34680456, 2021). "Subsequently, the HPMCs facilitated the invasion of ovarian cancer cells via submitting CD44-overexpressed exosomes to the cancer cells." (PMID 34078414, 2021). "Ovarian cancer stem cells (OCSCs) are characterized by the presence of CD44, CD117, CD133, and CD24, as well as ALDH activity." (PMID 34439332, 2021). "Compared to CD19NK and untransduced NK-92 cells, CD44NK showed potent and specific cytotoxic activity against CD44-positive ovarian cancer cell lines (SKOV3 and OVCAR3) and primary ovarian cancer cells harvested from ascites." (PMID 34680456, 2021). "CD44 has been demonstrated to interact with HA at the N terminus of its extracellular domain, and therefore serves as a major cell surface receptor for ovarian cancer." (PMID 34949180, 2021). "Researches have confirmed that integrin α5β1/AEP and CD44 mediated by exosomes derived from ovarian cancer cells can induce the destruction of the mesothelial barrier." (PMID 34725902, 2021). "The binding of HA to CD44 was shown to mediate ovarian cancer cell adhesion to peritoneal mesothelial cells." (PMID 34680456, 2021). "For example, ALDH1-bright cells from ovarian cancer cell lines show increased CD44 expression and inhibition of CD44 was shown to inhibit growth of sphere-forming ovarian cancer cells." (PMID 34680456, 2021). "This highlights the importance of combinatorial treatment of chemotherapy and CD44-targeted therapy in ovarian cancer." (PMID 34680456, 2021). "The ligand HA was chosen, as HA was tumor-specific for receptor cluster of differentiation 44 (CD44), a membrane-anchored cell surface receptor usually detected in ovarian cancer cells, such as SKOV3 and SKOV3TR cells." (PMID 34949180, 2021). "On the other side, CD44 expression has been associated with high-grade and advanced FIGO stage ovarian carcinomas." (PMID 32423054, 2020). "Ovarian cancer cells secrete exosomes enriched for CD44 to assist with attachment of cancer cells to HA expressed on mesothelial cells." (PMID 32780245, 2020). "Our data also showed in OV-90 cells a reduced expression of CD44, a putative ovarian cancer stem cells markers, this suggesting a possible role for KFL7 in promoting HGSOC progression also by enhancing cancer stem cell properties." (PMID 33250051, 2020). "Human peritoneal mesothelial cells (HPMCs) uptake exosomes containing CD44 that are released from ovarian cancer cells; therefore, CD44 is elevated in the HPMCs and induced MMP9 secretion which promote tumor invasion." (PMID 32499786, 2020). "TNF-α, secreted by adipocytes, differentially modulates the expression of CD44 in ovarian cancer cells." (PMID 32967712, 2020). "CD44+ and CD44-negative (CD44-) ovarian cancer cell fractions have been described as Type I chemoresistant and Type II chemosensitive EOC cells, respectively." (PMID 33335857, 2020). "More importantly, in ovarian cancer cells, a natural compound from Tripterygium wilfordii, Celastrol, promotes apoptosis by decreasing CD44 expression and STAT3 phosphorylation." (PMID 33335857, 2020). "Another selectin ligand proteoglycan that is overexpressed in ovarian cancer is CD44, at least some isoforms." (PMID 32785160, 2020).
ovarian carcinoma (continued). "HA binding to CD44 has been shown to promote ovarian cancer cell migration by recruiting Src and promoting cortactin-mediated cytoskeleton function." (PMID 31898491, 2020). "The embryonic stem cell marker Nanog interacts with the cancer stem cell marker CD44 to activate the STAT3 pathway in ovarian cancer cells." (PMID 33023532, 2020). "Of interest, CD44+ ovarian CSCs show preference for glycolysis as well, which indicates an important role for CD44 in ovarian cancer stemness maintenance via metabolism regulation." (PMID 33335857, 2020). "As with CD44, STAT3 signaling has been frequently implicated in ovarian cancer metastasis, therapy resistance, and CSC maintenance." (PMID 33335857, 2020). "MicroRNA 199a was shown to target CD44 to suppress the tumorigenicity and multidrug resistance of ovarian cancer-initiating cells CD44+/CD117+." (PMID 33233552, 2020). "In terms of drug resistance, CD44 was elevated in ovarian cancer cells and involved in paclitaxel resistance." (PMID 32642575, 2020). "CD44 is a transmembrane glycoprotein that is overexpressed in ovarian cancer and has been shown to promote cell proliferation by signaling through the MAPK pathway." (PMID 32850313, 2020). "Collectively, these findings indicate a pivotal role for CD44 in therapy resistance development, which is currently a major challenge in the treatment of ovarian cancer patients." (PMID 33335857, 2020). "Studies on the biological role of CD105 in ovarian cancer revealed that high CD105, CD44, or CD106 expression was associated with drug resistance, an advanced stage of the disease, poor differentiation, and high rate of cancer relapse." (PMID 33266317, 2020). "Other than mucins, important known selectin ligands in ovarian cancer include glycosaminoglycans like heparan sulfate and chondroitin sulfate, and some other glycoproteins like CD44 and CD24." (PMID 32785160, 2020). "Ovarian cancer cells/cell lines derived from ascites were used for tumourspheres/ALDH+CD44+ subset isolation." (PMID 32390009, 2020). "CD44+/CD117+ cells are ovarian cancer-initiating cells (CIC) that are characterized by their highly proliferative capabilities and their resistance to chemotherapies." (PMID 32850313, 2020). "Another study reported that scaffold/adaptor growth factor receptor bound 2-associated binding protein 2 (GAB2)-PI3K signaling enhanced EMT characteristics and the expansion of CSC-like cells via microRNA-200c/CD44 axis in ovarian cancer." (PMID 33303029, 2020). "This supports CD44 as a promising clinical target for the development of novel ovarian cancer therapeutics." (PMID 33335857, 2020). "Inhibition of CD44 had been reported to limit intra-abdominal spread of ovarian cancer cell in nude mice." (PMID 32967712, 2020). "At the same time, CD44 knockdown significantly enhances paclitaxel, cisplatin, and doxorubicin sensitivity in ovarian cancer cells." (PMID 33335857, 2020). "CD44 surface expression has been linked to cancer stem cells (CSCs), in ovarian and other cancer models, and most studies about the role of CD44 in ovarian cancer progression emphasize the connection between CD44 and CSC maintenance." (PMID 33335857, 2020). "Using a threshold of 25% CD44+/CD24–ve ovarian cancer cells found in ascites, patients with >25% CD44+/CD24−ve were significantly more likely to have recurrence (83 vs. 14%, P=0.003) and had shorter median progression-free survival (6 vs. 18 months, P=0.01)." (PMID 32684928, 2020). "To clarify the clinical importance of this “cross-talk” as a mechanism of drug resistance, we assessed the expression both of PKM2 and of CD44 in cancer cells of patients with epithelial ovarian cancer (EOC) treated with platinum-based treatment." (PMID 32326107, 2020). "In this study, we found a higher expression level of CD44 gene in recurrent tumor samples compared to primary tumors, but others have found the opposite in larger cohorts of ovarian cancer samples." (PMID 33352957, 2020).
ovarian carcinoma (continued). "Based on these findings, we conclude that dual positivity for ALDH and CD44 defines a compelling marker set for isolation of the CSC subpopulation of ovarian cancer." (PMID 32390009, 2020). "CD44+/CD177+ cells are ovarian cancer-initiating stem cells (CIC), which are known to be highly proliferative and resistant to chemotherapeutics, with low differentiation capabilities." (PMID 32850313, 2020). "According to the recently published data, the FKBPL-derived peptide, ALM201, reduced the numbers of CSCs in ovarian cancer cell lines and xenografts by targeting the CD44/STAT3 pathway and inhibiting angiogenesis." (PMID 32268506, 2020). "For instance, targeting CD44 using HA-labeled nanoparticles overcame chemoresistance with a higher efficiency in an ovarian carcinoma PDX model." (PMID 32825245, 2020). "Our data also showed that ZEB1, Snail, and Caveolin-1 are regulated by CD44, indicating the crucial role of CD44 in the initiation of EMT in ovarian cancer." (PMID 31497537, 2019). "The design of targeting CD44 is already employed to enhance drug efficacy and reduce systemic toxicity in ovarian cancer." (PMID 30818864, 2019). "Multivariate analysis showed that CD44 expression was an independent prognostic factor to predict both overall survival (p = 0.004) and disease-free survival (p = 0.025) of ovarian cancer patients." (PMID 31497537, 2019). "For example, CD44 expression can be decreased by interferon gamma (IFNg) in ovarian carcinoma cells." (PMID 31856847, 2019). "Although HOPM is a highly metastatic ovarian cancer cell line, its endogenous expression of Snail is low, so that it is difficult to observe the effect of CD44 on Snail expression using this cell line." (PMID 31497537, 2019). "CD44 positive epithelial ovarian cancer stem cells were also found to be correlated with drug resistance and recurrence." (PMID 30818864, 2019). "Some studies found that increased expression of CD44 closely correlated with poor prognosis of ovarian cancer." (PMID 31497537, 2019). "For example, the addition of recombinant protein secreted frizzled-related protein 4 (sFRP4) has been positively associated with response to cisplatin and doxorubicin in cancer stem cells (CD133+/CD44+) isolated from A2780 ovarian cancer cell line." (PMID 30894224, 2019). "Similar to our results, studies reported that ovarian cancer patients with positive expression of CD44 variant had a significantly shorter DFS, while low levels of CD44 expression was associated with better survival." (PMID 31497537, 2019). "Collectively, our findings demonstrate that fluorescent HA-SA NPs harboring a cytotoxic drug cargo can specifically target, label CD44-expressing ovarian cancer cells and efficiently eradicate them." (PMID 31060303, 2019). "The aim of the current study was to form prototype theranostic tracer-HA-SA conjugate-based NPs, characterize their self-assembly, drug loading and selective cytotoxicity to human ovarian cancer cells overexpressing CD44." (PMID 31060303, 2019). "We have loaded them with PTX and demonstrated their selective uptake by CD44-overexpressing human ovarian cancer cells followed by eradication of these malignant cells." (PMID 31060303, 2019). "We found that adding HA to CBP-treated cells only increased survival of ovarian cancer cell lines expressing the HA receptor CD44." (PMID 31443261, 2019). "Materials and Methods: The expression of CD44 in tissue microarray of 90 ovarian cancer patients was detected by immunohistochemistry." (PMID 31497537, 2019). "Liposomal NP (LNP) incorporated paclitaxel or coated anti-CD44 antibody loaded with a suicide gene or doxorubicin induced therapeutic effects in CD44-positive metastatic ovarian cancer cells or hepatocellular carcinoma cells." (PMID 31013960, 2019). "The precise interactions among STAT3, ALDH1A3, and CD44 in ovarian cancer require further assessment." (PMID 31534498, 2019).
ovarian carcinoma (continued). "Despite of clear poor prognostic value of CD44 in tumors such as breast and renal cell carcinomas, CD44 expression is a favorable predictor in ovarian cancer." (PMID 30909497, 2019). "After cisplatin treatment, the dormant cells of human ovarian cancer displayed an augmented expression of cells with Oct-4, nestin, CD-117, and CD44 markers, proving the resistance of this stem cell fraction to cisplatin." (PMID 31083587, 2019). "In a recent study, we have demonstrated that the human SKOV3 CD117+CD44+ CSC vaccination elicited strongly immune responses against ovarian cancer and significantly led to suppressing tumor xenografted growth in nude mice." (PMID 31008116, 2019). "CD44 is overexpressed in the peritoneal mesothelial cells of ovarian cancer patients with omental metastasis." (PMID 31409361, 2019). "We also evaluated the expression of CD44 in a series of ovarian cancer cell lines with different invasive potential." (PMID 31497537, 2019). "We observed that ovarian cancer VM-associated cells were able to secrete SDC1 and B-FN and expressed the stem cell markers CD44 and EpCAM." (PMID 31443604, 2019). "Higher expressions of AKT1 and CD44 genes in ovarian cancer patients had higher probabilities of survival than their lower expressions." (PMID 31752757, 2019). "Correlation of clinicopathological characteristics with CD44 expression in 90 ovarian cancer patients." (PMID 31497537, 2019). "Another study conducted in the US also reported that the expression of standard CD44 (CD44s) was significantly associated with worse DFS both in univariate (p = 0.003) and multivariate (p = 0.006) analysis in 56 patients with epithelial ovarian cancer." (PMID 31497537, 2019). "The gene can drive tumor progression in ovarian cancer through the NF-κB pathway by activating a regulatory factor cell surface molecule CD44." (PMID 30704472, 2019). "In this study, gPTX-loading liposomes conjugated with anti-CD44 antibody (gPTX-IL) were assessed for the efficacy of targeting CD44-positive ovarian cancer cells." (PMID 30818864, 2019). "Ovarian cancer PGCC derived tumor were CD133+/CD44+ and exhibit mesenchymal phenotype and chemoresistance." (PMID 31337825, 2019). "HA is a ligand for the receptor CD44, which is highly over‐expressed on most ovarian cancer cells, and hence functions as a targeting layer on the NPs." (PMID 31249881, 2019). "First, we assessed the protein and mRNA expression levels of CD44 in the ovarian cancer cell lines SK-OV-3, OVCAR-3, and OVK18." (PMID 30818864, 2019). "CD44 immunohistochemistry was used to assess ovarian cancer cell invasion from the ectoderm into the mesoderm layer of the CAM." (PMID 31443261, 2019). "These CAF-related molecules further confer the aggressiveness of ovarian cancer cells through the activation of NF-κB signaling pathway and the up-regulation of CD44, MMP9 and hyaluronan-mediated motility receptor (HMMR)." (PMID 31888563, 2019). "In conclusion, our study suggested that high expression of CD44 was correlated with poor prognosis of ovarian cancer patients." (PMID 31497537, 2019). "The immunohistochemistry data showed that CD44 was almost undetectable in healthy ovarian tissues while mainly located in the nuclei of ovarian cancer tissue." (PMID 31497537, 2019). "In another study, the downregulation of CD44 protein by siRNA in cancer cells from patients with ovarian carcinoma confirmed that the mRNA levels of CD44 and ABCB1 correlate positively." (PMID 31921125, 2019). "In summary, gPTX-IL was successfully demonstrated reduction of tumor volume and the therapeutic efficacy against CD44-overexpressing ovarian cancer cells in vivo." (PMID 30818864, 2019). "A subsequent study confirmed the low expression of miR-199a in ovarian cancer-initiating cells and has also shown that this microRNA targets CD44." (PMID 29389895, 2018).